IGF2BP3 (insulin like growth factor 2 mRNA binding protein 3)
Diseases named in the same sentence as IGF2BP3 in open-access papers (continued):
Sharing a sentence is not in itself a finding about the gene and the disease.
tumor (continued). "Additionally, the expression of most of the regulators influences the tumor T feature of KIRC, LIHC, PRAD, STAD and THCA, especially IGF2BP1 in BRCA; IGF2BP2, IGF2BP3, LRPPRC, and METTL14 in KIRC; and IGF2BP3 in KIRP." (PMID 39457524, 2024). "Furthermore, immunohistochemical (IHC) staining was performed to determine the expression of IGF2BP3 in HCC and peri-tumor tissues." (PMID 38992083, 2024). "In contrast, in CRC, IGF2BP3 inhibits VEGF expression, thereby reducing tumor angiogenesis." (PMID 39295872, 2024). "We therefore hypothesized that IGF2BP3 could elevate HMGB1 expression and promote tumor progression." (PMID 38504159, 2024). "Moreover, it was observed that IGF2BP3 increased the expression of MMP9, which stimulates tumor invasion and metastasis via the degradation of the extracellular matrix and is also important for EMT." (PMID 38504159, 2024). "This demonstrates the dual role of IGF2BP3 and HMGB1 in tumor development and treatment." (PMID 38504159, 2024). "In addition, there was a significantly positive correlation between the IGF2BP3 and NFAT1 mRNA expressions in tumor tissues from 414 cases with GC in the OncoDB database." (PMID 38448411, 2024). "The expression of the regulators significantly varies based on tumor stage in a few cancers, including KIRP, KIRC, KICH, LIHC, OV, THCA, and TGCT; IGF2BP2 in KIRC and THCA; IGF2BP3 in KIRP, KIRC, and UCEC; and LRPPRC and METTL14 in KIRC are the ones that are the most varied." (PMID 39457524, 2024). "The analysis showed that the methylation levels of the majority of the CpG sites we examined showed a strong negative correlation with the IGF2BP3 mRNA levels in various tumor types from the TCGA datasets, including TCGA BLCA." (PMID 38504159, 2024). "In brief, IGF2BP3 also acts as a tumor-promoting factor in CRC, and the regulation of IGF2BP3 expression may serve as a strategy to inhibit CRC progression." (PMID 37298373, 2023). "Correlation analysis between IGF2BP3 expression and clinicopathologic characteristics of the 28 HSCC patients showed that high IGF2BP3 expression did not correlate with tumor size (P>0.05), tumor grade (P>0.05), or tumor-node-metastasis (TNM) stage (P>0.05)." (PMID 37859812, 2023). "These outcomes suggest that the tumor suppressor effect of ANXA10 is related to m6A; ANXA10 may regulate HNRNPA2B1, IGF2BP3, METTL3, RBM15, YTHDF1 and YTHDF2 to affect the methylation level of LIHC." (PMID 36709331, 2023). "IGF2BPs, particularly IGF2BP1 and IGF2BP3, are widely recognized as oncofetal proteins predominantly expressed in cancer rather than normal tissues, playing a critical role in tumor initiation and progression." (PMID 37280679, 2023). "This study uncovers a mechanism for tumor metastasis in NPC, suggesting that inhibition of IGF2BP3 might be a promising strategy." (PMID 37853162, 2023). "Among these proteins, knockdown of the IGF2BP3 gene inhibits hypoxia-induced angiogenesis in vivo by downregulating HIF1A, which inhibits angiogenesis mainly by reducing the expression of pro-angiogenic factor (VEGF) in tumor tissues." (PMID 38053093, 2023). "Intriguingly, IGF2BP3 could stabilize MYC and increase its expression, establishing a positive feedback mechanism to expedite tumor deterioration." (PMID 37554271, 2023). "IGF2BP3 expression, however, was not significantly different between tumor and normal tissue in PCPG, READ, and TGCT." (PMID 36732736, 2023). "As another member of the IGF2BP family, IGF2BP3 reportedly promotes eIF4E‐mediated translational activation by decreasing the stability of EIF4E‐BP2 mRNA, which in turn enhances the proliferation of tumour cells." (PMID 35876041, 2022). "Since METTL3-mediated m6A modification could enhance PD-L1 mRNA stability through the METTL3-IGF2BP3 axis, tumor immune cell infiltrations and CD8+ T cell functions were enhanced forcefully when METTL3 or IGF2BP3 is inhibited." (PMID 36035182, 2022).
tumor (continued). "For instance, circNEIL3 contained in exosomes secreted by glioma cells accelerates tumor evasion of immune surveillance by blocking HECTD4-mediated ubiquitination to stabilize the m6A methylation regulator, IGF2BP3, and promote an immunosuppressive phenotype in macrophages." (PMID 35794625, 2022). "Mechanistically, IGF2BP3 could serve as an m6A “reader” to recognize m6A modified mRNA and enhance HDGF mRNA stability to promote tumor angiogenesis and glycolysis in GC." (PMID 35986300, 2022). "Further, we also found the m6A methylation-related genes FTO, IGF2BP3, and YTHDC1 might participate in the process of PGM1 methylation modification, thereby affecting tumor progression and metastasis." (PMID 35251177, 2022). "In terms of methylation, the expression level of ECE2 was significantly negatively correlated with HNRNPC, IGF2BP1, IGF2BP3 and RBM15, which may affect the tumor progression of LUAD by affecting the m6A methylation level." (PMID 36299451, 2022). "Highly expressed IGF2BP3 can directly bind to the m6A-modified region of target mRNA, thereby promoting the stability and expression of specific genes, such as TMBIM6, VEGF, and ABCB1, leading to tumor progression, angiogenesis, and chemoresistance." (PMID 35136045, 2022). "In addition, YTHDC1, YTHDF1, YTHDF2, IGF2BP3, HNRNPA2B1 and NKAP were confirmed by two databases to be positively correlated with tumor stage, which deserved more attention in the treatment of HCC." (PMID 35963644, 2022). "In particular, the results of this and other studies showed that IGF2BP3 also stimulated the progression of KIRC and that IGF2BP3 levels in tumor tissues, and peripheral blood could be used as a predictor of KIRC metastasis and clinical prognosis." (PMID 33608495, 2021). "Notably, IGF2BP3 sustained IGF2 and IGF1R mRNA translation in tumor cells but any involvement of the IGF2BP3/IGF2/IGF1R axis in response to BET inhibitors has not been yet established." (PMID 34440844, 2021). "Additionally, knockdown of IGF2BP3 also repressed the expression of Cyclin D1, Ki67 (the marker for tumor proliferation), VEGF, and CD31 (the marker for tumor vessels) in vivo." (PMID 32993738, 2020). "In the grid in the center of the table, blue indicates low expression of IGF2BP3 in the corresponding tumor, red indicates high expression, and gray indicates no data." (PMID 32984260, 2020). "One of the two down-regulated genes–IGF2BP3 is not expressed in normal adult tissues and is known to promote tumor invasion and metastasis." (PMID 31150395, 2019). "Among the IGF2BPs, IGF2BP3 has been particularly described to favor IGF2 translation, thereby activating IGF signaling and promoting cell growth, proliferation, and resistance to ionic irradiation in different tumor types." (PMID 29731738, 2018). "In the case of IMP3/IGF2BP3, staining was only detected in the smooth muscle cells across tumor and adjacent normal regions, but not in tumor, normal cells, or stroma (data not shown)." (PMID 22280838, 2012). "Disease specific survival for all tumor grades was found to be significantly shorter in patients with IGF2BP3 expressing tumors than in those with IGF2BP3 non-expressing tumors (9.3 months vs. 13.7 months, respectively, P = 0.024)." (PMID 20178612, 2010). "This regulatory relationship between MYO16-AS1 and IGF2BP3 might be present mainly in tumor epithelial cells rather than mesenchymal cells or immune cells." (PMID 38041756, 2024). "Interestingly, as we have recently demonstrated, extracellular vesicles derived from IGF2BP3-positive versus IGF2BP3-negative cells differentially influenced the phenotype of tumor recipient cells." (PMID 38892104, 2024). "However, IGF2BP3 participated in the tumour progression as an RNA‐binding protein and did not involve m6A‐related mechanism in these studies." (PMID 37743642, 2023).
tumor (continued). "The mRNA expression levels of YTHDC2, YTHDF1, YTHDF3, IGF2BP1, and IGF2BP3 were significantly increased in tumour tissues compared with paired normal breast tissues, while the METTL14, WTAP, FTO, and IGF2BP2 expression levels were significantly decreased in tumour tissues." (PMID 36632454, 2023). "Collectively, all these data indicated that LINC00958 might exert its tumor-promoting effects by binding with IGF2BP3, not regulating it, in EC." (PMID 35676262, 2022). "Stronger IGF2BP3 staining was detected in 122 LSCC compared with adjacent non-tumor tissues." (PMID 33637103, 2021). "siIGF2BP3 showed a greater reduction of tumor weight and volume than negative controls, suggesting that inhibiting IGF2BP3 could delay the tumor growth in vivo." (PMID 32083017, 2019). "We found that the majority of tumor tissue samples expressed a higher level of IGF2BP3 than the corresponding adjacent non-cancerous tissue samples at both the mRNA and protein levels, suggesting that a high level of IGF2BP3 expression is a predictor of poor prognosis in HCC patients." (PMID 26327240, 2015). "Mechanistically, IGF2BP3 maintains NOTCH3 mRNA stability via suppression of CCR4-NOT complex-mediated deadenylation in an m6A-dependent manner, which sustains Notch3 signaling activation and increases the transcription of stemness-associated downstream genes, eventually promoting tumor metastasis." (PMID 37853162, 2023). "Furthermore, IGF2BP3 diminishes the ability of natural killer cells to recognize transformed cells by downregulating the stress-induced ligands UL16 binding protein 2 (ULBP2) and major histocompatibility complex class I polypeptide-related sequence B (MICB), contributing to tumor immune evasion." (PMID 37554271, 2023). "IGF2BP3 showed a spatiotemporal expression pattern of “high expression during embryogenesis, inhibited expression in the normal intestinal mucosa, and upregulated expression in CRC tissues,” suggesting that IGF2BP3 might be involved in tumorigenesis and tumor progression of CRC." (PMID 37658049, 2023). "Finally, 8 genes related to anti-tumor immunity were obtained, which were APOL3, CCL5, CD8A, CD8B, CXCL9, GZMA, GZMK and PRF1.We found that the m6A regulatory factors YTHDC1, YTHDC2, and WTAP were positively correlated with m6A, while IGF2BP3 was negatively correlated." (PMID 34737950, 2021). "This suggests that IGF2BP3 is not essential for cell growth and viability in MCC but primarily contributes to tumor progression." (PMID 40162116, 2025). "Similar to the DEN-induced HCC progenitors, these lesions expressed IGF2BP3 and were LIN28B but not LIN28A positive, suggesting a greater importance for LIN28B in tumor initiation." (PMID 38875287, 2024). "Based on TCGA database, we discovered that expressions of IGF2BP2 and IGF2BP3 were significantly upregulated in ESCA tissues compared with normal tissues, and the expressions of the other 12 RBPs were not altered in tumor tissues versus normal tissues." (PMID 32239639, 2020). "They demonstrated that IGF2BP3 increases the IGF-2 protein level without increasing its transcript level, and promotes tumor growth by activating downstream effectors such as PI3K and MAPK." (PMID 30760837, 2019). "In 30 paired tumor and adjacent noncancerous liver tissues from HCC patients, we analyzed the expression levels of IGF2BP3 via real-time RT-PCR and western blot." (PMID 26327240, 2015). "Further analysis found lentiviral-mediated IGF2BP3 knockdown could overcome CDDP resistance in xenografts generated from T24R cells, as demonstrated by significantly reduced tumor growth in CDDP-treated xenografts than those without CDDP treatment." (PMID 39680264, 2024). "Notably, IGF2BP3 knockdown in K562 cells (chronic myeloid leukemia) does not induce apoptosis by itself, an observation we can also confirm for IGF2BP1 in tumor cells derived from gastrointestinal cancers (unpublished)." (PMID 23069990, 2013).
cancer (240 papers, 2003 to 2026). A tumor composed of atypical neoplastic, often pleomorphic cells that invade other tissues. "Among them, IGF2BP3 has high expression levels and is associated with poor survival rates in various cancer types, and it has been identified as a potential oncogene for multiple types of cancer." (PMID 41589308, 2025). "CircNEIL3 has been discovered to accelerate the development of gliomas and tumors by maintaining the cancer‐causing protein IGF2BP3 and preventing HECTD4 from mediating ubiquitination." (PMID 40919129, 2025). "The knockdown of BIM partially counteracted the increased apoptosis in cancer cells caused by IGF2BP3 knockdown." (PMID 40801655, 2025). "Previous research has indicated that IGF2BP3 is often overexpressed in different types of cancer, and is linked to the advancement of tumors, their spread to other parts of the body, and poor prognosis." (PMID 40672753, 2025). "In summary, this study demonstrates that IGF2BP3 is highly expressed in gastrointestinal cancers and is associated with both diagnostic and prognostic factors in these cancers." (PMID 40765570, 2025). "Our findings reveal that OLFML1 expression is regulated by insulin-like growth factor 2 mRNA-binding protein 3 (IGF2BP3), a well-known RNA-binding protein implicated in cancer progression." (PMID 40765816, 2025). "Among the other highly DEGs in this cluster, Nup88, Dmxl1 and Igf2bp3 are associated with dysplasia and cancer, including CRC." (PMID 40890536, 2025). "The IGF2BP family consists of three members including IGF2BP1, IGF2BP2, and IGF2BP3, all of which are implicated in the drug resistance of human cancers." (PMID 39731162, 2024). "For its part, insulin-like growth factor 2 mRNA-binding protein 3 (IGF2BP3) is associated with a poor prognosis implicated in several mechanisms leading to aberrant metabolism in cancer." (PMID 38779099, 2024). "IGF2BP3 has carcinogenic characteristics and is significantly up-regulated in numerous cancer subtypes, associating with poor survival." (PMID 38384328, 2024). "Different sets of prognostic signatures are identified for different cancers by us, and IGF2BP3, a well-known m6A regulator, is found to be highly expressed in a high-risk group of several cancers." (PMID 39457524, 2024). "Numerous studies, including our own, have shown that IGF2BP3 is a cancer-causing factor and frequently exhibits high levels of expression in various types of cancer." (PMID 38504159, 2024). "Then, a close positive association between IGF2BP3 expression and several immune scores was detected in pan-cancer analysis." (PMID 36761737, 2023). "It is important to mention that IGF2BP3 is tightly associated with both immune and molecular subtypes in four types of cancers, including LGG, LUSC, BRCA, and COAD." (PMID 36761737, 2023). "Further, each cancer’s survival analysis was performed to investigate the association between IGF2BP3 expression level and prognosis, concentrating on OS, DSS, and PFI." (PMID 36761737, 2023). "Meanwhile, IGF2BP3 was significantly associated with diverse molecular subtypes in nine cancer types." (PMID 36761737, 2023). "Further, we assessed the associations between IGF2BP3 and different clinical characteristics in pan-cancer." (PMID 36761737, 2023). "The 16 m6A-regulated enzymes in NB were researched, and the result indicated that IGF2BP3 overexpression was related to cancer progression, COG risk, and survival based on the GEO and TARGET databases." (PMID 37156775, 2023). "As an RNA binding protein, the function of IGF2BP3 is intimately linked to the cancer cells’ unique transcriptional program." (PMID 37760460, 2023). "In gastrointestinal cancer, for example, increased IGF2BP3 expression has been linked to a poor prognosis, increased cancer cell proliferation, and metastasis." (PMID 38092752, 2023).
cancer (continued). "Located on chromosome 7p15.3, IGF2BP3 encodes an oncofetal protein expressed during embryogenesis, virtually absent in normal adult tissues, and strongly re-expressed in cancer cells." (PMID 37760460, 2023). "As in other cancer types, IGF2BP3 overexpression was found to be associated with aggressive behavior in B-ALL." (PMID 36307883, 2022). "Previous studies found that the expression of IGF2BP3 was associated with the occurrence, metastasis, and poor prognosis of malignant tumors." (PMID 35033075, 2022). "IGF2BP3 was significantly associated with Cancer associated fibroblast (r = 0.2, p = 7.24e–03), Myeloid dendritic cell (r = 0.17, p = 2.22e–02)." (PMID 33748145, 2021). "We investigated IGF2BP3, which has previously been associated with aggressive cancers, and found high and subtype-specific expression of IGF2BP3 in B-cell ALL, that was associated with good outcome in high-risk patients." (PMID 33805930, 2021). "IGF2BP3 overexpression has been linked to advanced disease stage and adverse clinical outcome in several cancers." (PMID 33094561, 2020). "Insulin-like growth factor-2 messenger RNA-binding protein 3 (IGF2BP3 or IMP3) is an oncofetal protein that is expressed in various cancer types, and its expression is often associated with poor prognosis." (PMID 32293476, 2020). "IGF2BP3 shows oncogenic features and is markedly up-regulated in a variety of cancer types, associated with poor patient survival." (PMID 31801551, 2019). "Nonetheless, the bulk of correlative studies associating the upregulation of IGF2BP3 with various malignancies provide strong evidence for a pivotal role of IGF2BP3 in cancer." (PMID 23069990, 2013). "This analysis identified 4 SNPs significantly associated with UCEC, including rs10757268, rs1412832, rs2095144, and rs8181047, suggesting these SNPs might modulate IGF2BP3 expression, thereby contributing to cancer risk." (PMID 39883704, 2025). "And more importantly, the causes of aberrant IGF2BP3 expression in cancer is poorly understood." (PMID 38504159, 2024). "This upregulation was linked to the promotion of the progression of eESCs, indicating that IGF2BP3 may have diagnostic value for EMs cancer." (PMID 38760723, 2024). "To determine whether known targets of LIN28A/LIN28B would be able to rescue cancer initiation in Lin28a/Lin28b-deficient mice, we tested Igf2bp1, Igf2bp2, and Igf2bp3." (PMID 38875287, 2024). "Additionally, IGF2BP3 is critically associated with genetic markers of immunomodulators in various cancers." (PMID 36761737, 2023). "IGF2BP3 might be a pan-cancer oncogene, as its overexpression is associated with poor patient survival in various cancers, including kidney renal clear cell carcinoma, kidney renal papillary cell carcinoma, brain lower-grade glioma, and more." (PMID 37280679, 2023). "Besides, both the diagnostic utility and predictive value of IGF2BP3 in the pan-cancer TCGA cohorts were evaluated." (PMID 36761737, 2023). "IGF2BP3 expression is associated with poor prognosis in cancers of multiple tissue origins." (PMID 36732736, 2023). "As dysregulated IGF2BP3 was implicated in the process of RNA regulation and transcription in cancer, we further investigated whether IGF2BP3 was associated with the mutation of cancer-related genes." (PMID 36761737, 2023). "IGF2BP3 is abnormally expressed in many human cancers, often associated with poor prognosis." (PMID 37298373, 2023). "Moreover, IGF2BP3 was also implicated in the regulation of cancer stemness, metabolism and immunity." (PMID 34894048, 2022). "Previous studies indicated that IGF2BP3 may act as a diagnostic biomarker for various cancers due to its abnormal expression in tumors." (PMID 36401176, 2022). "IGF2BP3 has gained considerable interest as a cancer-associated protein." (PMID 33297932, 2020). "In future, whether IGF2BP3 is a useful diagnostic marker to predict malignant status or distinguish malignant tumors from benign tumors in diverse tumors will be intriguing." (PMID 29212181, 2017).